PARVG (parvin gamma)
Description:
Plays a role with ILK in promoting the cell adhesion and spreading of leukocytes.
Tractability: Antibody: UniProt places it where antibodies can reach, with medium confidence; its Gene Ontology location is reachable by antibodies, with medium confidence. PROTAC: ubiquitination databases record sites on it; its protein half-life has been measured.
Target class: Adhesion
Gene: Protein-coding gene on chromosome 22 (44,172,956 to 44,219,533, forward strand). Ensembl gene ENSG00000138964.
Subcellular location: Cell junction, focal adhesion; Cell membrane; Cytoplasm, cytoskeleton
Gene Ontology:
Molecular function: protein binding; actin binding
Biological process: actin cytoskeleton organization; cell-matrix adhesion; establishment or maintenance of cell polarity regulating cell shape; substrate adhesion-dependent cell spreading; cell adhesion
Cellular component: actin cytoskeleton; cytoplasm; cytoskeleton; focal adhesion; plasma membrane
Genetic constraint (gnomAD): Loss-of-function variants: 35 observed, 44.74 expected, observed/expected ratio (o/e) 0.78, 90% interval 0.6 to 1.04. The upper end of that interval is the gene's LOEUF score, 1.04, which puts it in group 4 of 6, group 1 being the genes least tolerant of losing a copy. Missense variants: 400 observed, 417.14 expected, observed/expected ratio (o/e) 0.96, 90% interval 0.88 to 1.04. Synonymous variants: 165 observed, 178.57 expected, observed/expected ratio (o/e) 0.92, 90% interval 0.81 to 1.05.
Homologues: Orthologues: chimpanzee PARVG (99% identical), macaque PARVG (88% identical), pig PARVG (84% identical), dog PARVG (82% identical), mouse Parvg (79% identical), rat Parvg (79% identical), guinea pig PARVG (56% identical), tropical clawed frog parvg (51% identical), zebrafish parvg (50% identical), Drosophila melanogaster parvin (37% identical), Caenorhabditis elegans pat-6 (33% identical). Paralogues in human: PARVB (42% identical), PARVA (41% identical).
Diseases named in the same sentence as PARVG in open-access papers:
PARVG is named in the same sentence as 12 diseases in open-access papers, as found by Europe PMC text mining. Sharing a sentence is not in itself a finding about the gene and the disease. The quoted sentences say what the papers report.
breast carcinoma (2 papers, 2017 to 2021). "Furthermore, PARVG, located on 22q13, was identified as a candidate tumor suppressor gene for colorectal and breast cancer, and ILK-γ-parvin complex was revealed to be critically involved in the initial integrin signaling for leukocyte migration." (PMID 28029655, 2017). "PARVG, located in the q13.31 region of chromosome 22, has been proven not to be a tumor suppressor gene related to the occurrence and development of CRC and breast cancer." (PMID 34246261, 2021).
adenoid cystic carcinoma (1 paper, 2021). A malignant tumor arising from the epithelial cells. "The results of a methylation sequencing study on adenoid cystic carcinoma found that PARVG in tumor tissues showed lower methylation levels." (PMID 34246261, 2021).
diabetes (1 paper, 2022). "Most genes have been related to diabetes and cancer, with most of them being linked to pancreatic cancer (CEACAM6, HDAC5, HPCAL1, PARVG, and STYXL1)." (PMID 36360783, 2022).
renal carcinoma (1 paper, 2021). A carcinoma arising from the epithelium of the renal parenchyma or the renal pelvis. "In addition, a report showed that the high expression of the PARVG gene caused by low-level DNA methylation is significantly related to the poor prognosis of renal cancer patients." (PMID 34246261, 2021).
cancer (3 papers, 2021 to 2022). A tumor composed of atypical neoplastic, often pleomorphic cells that invade other tissues. "It was found that eight proteins (ADD2, DEF6, DOK3, ENO2, FMNL1, MICALL2, PARVG, and PSTPIP1) in KIRC cancer were more highly expressed in tumor tissues (100%), compared with normal tissues." (PMID 36428765, 2022). "Among them, we verified the difference in expression of PARVG and SYNE4 in 13 pairs of normal tissues and cancer tissues." (PMID 34246261, 2021).
PARVG also shares sentences with these, for which no sentence is quoted: tumor (3 papers); systemic lupus erythematosus (2); COVID-19 (1); endometrial carcinoma (1); osteosarcoma (1); pancreatic cancer (1); polycystic ovary syndrome (1).